NLRC4 (NLR family CARD domain containing 4)
Diseases named in the same sentence as NLRC4 in open-access papers (continued):
Sharing a sentence is not in itself a finding about the gene and the disease.
neurological diseases (4 papers, 2019 to 2022). "Besides the NLRP3 inflammasome, NLRC4 inflammasome was also shown to be implicated in neurological diseases." (PMID 31892810, 2019). "Not only NLRP3 and NLRC4 but also NLRP1 inflammasome were shown to have a role in neurological diseases." (PMID 31892810, 2019). "The activation of NLRP3, nucleotide oligomerization domain (NOD)-like receptor protein 1 (NLRP1), and NLR family CARD domain containing 4 (NLRC4), and the absence of Melanoma 2 (AIM2) inflammasomes are all associated with various neurological diseases." (PMID 31417409, 2019).
kidney diseases (3 papers, 2018 to 2025). "We established a network regulation map of circRNAs and miRNAs associated with NLRC4 based on a previous study that reported the parent gene of circRNAs involved in kidney diseases to further investigate the potential regulated mechanism of NLRC417–20." (PMID 35835791, 2022).
autosomal dominant disease (1 paper, 2019). Autosomal dominant form of disease. "Both phenotypes are autosomal dominant diseases caused by mutations in the NLRC4 gene, encoding NLRC4, which lead to a constitutive NLRC4 inflammasome activation resulting in an increased secretion of IL-1β and IL-18." (PMID 31736939, 2019).
cardiovascular diseases (1 paper, 2025). "Studies on NLRC4 activation in cardiovascular diseases are still preliminary." (PMID 40332346, 2025).
gastrointestinal disorders (1 paper, 2024). "A reduction in NLRC4 expression might lead to dysbiosis of the gut microbiome, increasing the risk for gastrointestinal disorders." (PMID 39292002, 2024).
vascular disorder (1 paper, 2017). A general term used to describe any disease affecting blood vessels]. "Complexes such as Bcl3/NF-kappaB2 complex (governed by BCL3 and NFKB2), vacuolar lumen (governed by CLN5), IPAF inflammasome complex (CASP1, CASP4, NLRC4) help to understand the involvement of inflammation and vascular disorder in AD." (PMID 28199395, 2017).
NLRC4 also shares sentences with these, for which no sentence is quoted: rheumatoid arthritis (4 papers); atopic dermatitis (3); acquired cold urticaria (2); Anxiety (2); cerebral artery (2); chorioamnionitis (2); conjunctivitis (2); gout (2); Kawasaki disease (2); lymphoproliferative disorders (2); parasite infection (2); Parkinson disease (2); Schnitzler syndrome (2); Acidosis (1); acute respiratory failure (1); amyotrophic lateral sclerosis (1); anaemia (1); antibody deficiency (1); autoimmune lymphoproliferative syndrome (1); bladder cancer (1); brain cancer (1); brain glioma (1); brain inflammation (1); breast tumor (1); Candidiasis (1); cholesteatoma (1); chronic eosinophilic pneumonia (1); chronic granulomatous disease (1); chronic periodontitis (1); chronic sinusitis (1).
A further 62 diseases each share a sentence with NLRC4 in 1 paper.